CD68 (CD68 molecule)
Diseases named in the same sentence as CD68 in open-access papers (continued):
Sharing a sentence is not in itself a finding about the gene and the disease.
tumor (continued). "Regions of interest (ROI) were selected based on Ki67 positivity (tumor-enriched regions) and immunofluorescence imaging of CD45, CD68, and tumor marker synaptophysin expression to scan tumor regions." (PMID 33228231, 2020). "CD68+-TAMs correlated with survival significantly in male GC patients, larger tumour size (diameter ≥ 5 cm), lymph node metastasis and tumour invasion depth T3." (PMID 32765828, 2020). "CD68-immunoreactive macrophages/microglia accounted for less than 10% of all cells in both the infiltration zone and the solid portion of the tumor." (PMID 32872536, 2020). "The three tumor models showed infiltration of human CD68+CD66b− TAMs and CD68−CD66b+ granulocytes, but to different degrees." (PMID 33013879, 2020). "CD68+ cells within the tumor niche exhibited more intensive infiltration in wild-type EGFR than in mutated tumors, and were related to lymph node invasion." (PMID 33194645, 2020). "A higher ratio of CD163+/CD68+ at the invasive front in comparison with the tumor center was also described elsewhere." (PMID 33371444, 2020). "Pathological assessment of the tumor tissues revealed that more CD68+ macrophages, especially CD206+ M2 macrophages, infiltrated the tumor stroma when tumor cells that highly expressed FOXO1 were in the marginal area." (PMID 33052231, 2020). "Immunofluorescence of 30 NET G3/NEC patients showed overall varied expression of synaptophysin, CD45, and CD68 as expected with such heterogenous tissues derived from distinct tumor sites, morphologies, and disease stages." (PMID 33228231, 2020). "Patients with higher expression of CD68 in tumor microenvironment have a tendency to have poor treatment outcome of DLBCL." (PMID 32731512, 2020). "Analysis of both peritumoural and intratumoural CD68+ macrophage infiltration correlated to differential expression of a number of genes within the tumour tissue." (PMID 32843682, 2020). "The therapeutic effect of BLZ945 on the infiltration of macrophages in the liver and spleen of tumour‐bearing mice after different treatments was further examined by IHC using an anti‐CD68 antibody." (PMID 33037771, 2020). "They rather observed a diffuse pattern of CD68+ macrophages, which correlated with high tumor grade, tumor necrosis, and large tumor size." (PMID 33377644, 2020). "The MIB-1 index was significantly correlated with diffuse infiltration of tumour-associated CD45+ lymphocytes (r = 0.63, p = 0.015) and CD68+ macrophages (r = 0.43, p = 0.021)." (PMID 32152754, 2020). "The formula of the F2P Score was developed and presented herein: F2P Score = 0.888 × (1.424 × tumor size-0.667 × age)+0.314 × (−0.259 × ESR1−0.191 × PGR−0.292 × BCL2−0.226 × GSTM1 −0.457 × CD68–0.320 × BAG1)." (PMID 33042787, 2020). "Multivariate analysis demonstrated that CD68+ TAMs, tumour diameter ≥ 5 cm and advanced TNM stage remained as significant independent prognostic factors of survival of male GC patients." (PMID 32765828, 2020). "For further verification of the expression of CD4/IFNGR2/CD68/CSF1R as immune signatures in OSA tumor microenvironment, RT-qPCR was performed using mRNA from 45 collected primary surgical tissue samples of OSA primary tumors." (PMID 32850346, 2020). "We found a statin dose-dependent reduction in protumorigenic TAMs (CD68+CD163+) in both stromal (P = .021) and parenchymal (P = .003) compartments within regions of in situ tumor growth, but this association was lost in invasive regions." (PMID 32190817, 2020). "In contrast to these studies, our results showed that high density of CD68+ cells correlated with small tumor size." (PMID 33211709, 2020). "In this study, we assess the prognostic significance of macrophage subpopulation densities and their ratios (CD68+, CD163+, and CD68+CD163− expressing cells) within different regions of the tumor (IM, CT, IMCT) using automated image analysis." (PMID 32435699, 2020).
tumor (continued). "Tumor-infiltrating macrophages have been classified as M1 (antitumor) or M2 (protumor) according to the co-expression of CD68, iNOS or MRC1/CD206, CD163, Arg1, and other markers in in vitro models." (PMID 32168749, 2020). "CD68 is used as a valuable cytochemical marker for immunostaining monocytes/macrophages in histochemical analysis of inflammation of tumor tissues." (PMID 33044562, 2020). "Dual labeling of GBMs for RSK1 and CD68 showed that both CD68‐ (majority of cells) and CD68+ cells within the tumor express RSK1, which implies that RSK1 can indeed derive from both tumor and immune infiltrate cells." (PMID 31701625, 2020). "We examined the macrophages infiltration in tumors at 8-week when tumor acquired resistance to bevacizumab, whereas CD68+ CD206+ for classic M2 macrophage and CD68+ CD86+ for M1 macrophage." (PMID 33214550, 2020). "IHC staining of 118 CRC tissues demonstrated positive association of intratumoral CD68+ TAM count with depth of invasion, lymph node metastasis, and tumor staging." (PMID 33194645, 2020). "Specifically, the tumor tissue expressed higher levels of cd14 and cd68 indicative of a greater presence of monocytes and macrophages in the tumor tissue compared with NAT." (PMID 32737216, 2020). "The CD68 mononuclear positive cells were significantly higher in tumour than in MSR squamous epithelium connective tissue and lymph node metastasis." (PMID 31870104, 2019). "An important additional finding describes the strong similarity in expression pattern between SMPD1 and CD68 for cells of the monocyte/macrophage lineage at the tumor site." (PMID 31049165, 2019). "Labeling for CD68, a commonly used marker of monocytes and tissue macrophages, identified cells located in normal alveolar lung tissue and along the margin of tumor foci." (PMID 31434729, 2019). "Conversely, B7-H3 expression in tumor-infiltrating immune cells was positively correlated with CD68-expressing cells." (PMID 30813210, 2019). "CD68+ TAMs in TIF were also correlated with reduced formation of multiple tumour nodules (p = 0.035)." (PMID 31170995, 2019). "We used CD68 immunofluorescence to detect macrophages in our TMAs and found CD68+ macrophages present in all tumor TMA spots of NSCLC cohorts (n = 240) in both the TI and TME." (PMID 31710308, 2019). "Consistent with previous reports, CD68, CD163, and CD14 antibodies strongly stained cells in the CHL tumor microenvironment in each of the variants." (PMID 31714922, 2019). "We confirm that within the group of BAP1-expressing tumours from Leiden, gain of 8q was associated with a higher mRNA expression of CD3 (lymphocytes, p = 0.026) and especially of more CD68 (macrophages, p = 0.007)." (PMID 31337000, 2019). "Tumor cell mitoses, CD68+ or CD163+ macrophages, CD47, calreticulin, or checkpoint molecules were not significantly different in these two groups." (PMID 30938231, 2019). "Immunofluorescence results demonstrated that treatment of tumors with S.t-ΔpGlux/pT-ClyA resulted in a significant increase in tumor infiltration by macrophages (CD68), dendritic cells (CD11c), and neutrophils (Ly-6G/Ly-6C)." (PMID 31754923, 2019). "Pre-chemotherapy CD68 staining correlated positively with the baseline SUVmax, and negatively with the percent of viable tumor cells in post-chemotherapy resection samples." (PMID 30999901, 2019). "The CD68++CD163+ macrophages (40%) were the next most abundant and the CD68+CD163+CD206+ macrophages remained the abundant population beyond 20 μm from the tumor cell." (PMID 31477692, 2019). "The tissues with RGC-32+CD68+ macrophages accounted for 64.6% of those with CD68+ macrophages in tumor specimens, and only 43% of those in normal tissues." (PMID 31601783, 2019). "High levels of tumor-infiltrating CD68+ M, CD163+ M2, and CD47 expression were significantly associated with worse survival." (PMID 31771616, 2019). "We therefore performed IHC with CD68 to better quantify the degree of macrophage infiltration of tumor specimens." (PMID 30999901, 2019).
tumor (continued). "Distances between cells within the tumor core were analyzed and identified the CD68+IRF8+ macrophages as the population located in closest proximity to the tumor cells with a median nucleus-to-nucleus distance of 12.3 μm." (PMID 31477692, 2019). "We observed that monocytes cultured with either IL32β or IL32γ express both CD68 and CD80, markers associated with M1 proinflammatory macrophages thought to play an anti-tumor role." (PMID 30953519, 2019). "The upregulation of cytokine-encoding genes in whole AC tumor tissue was found to correlate to the presence of an immune infiltrate and the expression of inflammatory cell markers, like CD14 and CD68." (PMID 31191748, 2019). "Overall survival (A) and disease free survival (B) curves of HCC patients in correlation with intra-tumor M2 level (CD206/CD68)." (PMID 31296243, 2019). "When patients of all subtypes (n = 86) were combined, the statistically significant inverse correlation (r = −0.23, p = 0.0373) between the amount of CD68+ cells and frequency of c-Myb+ tumor cells was revealed." (PMID 31406165, 2019). "We also examined macrophage presence in HNSCC tumor tissue using CD68 (pan-macrophage marker), iNOS (M1 marker) and CD163 (M2 marker)." (PMID 31379843, 2019). "For CD8+ cells and CD68+ cells, as well as CD66b+ cells infiltrating the tumour compartment, the prognostic value remained in multivariable analysis." (PMID 31882709, 2019). "In contrast, the CD68+CD163+CD206+ macrophages were furthest from the tumor cells (median distance 23.8 μm)." (PMID 31477692, 2019). "Next, we further investigated SIRT4 expression in CD68+ macrophages from tumours with different grades." (PMID 31744516, 2019). "Although CD68 is a well-known routinely used immunohistochemical marker of cells of monocyte/macrophage lineage, the function of CD68 in immunity, inflammation, and tumor biology is surprisingly poorly understood." (PMID 31049165, 2019). "Anti-CD68 showed a mild macrophage infiltrate within and around the tumor with increased density within foci of tumor necrosis, consistent with increased macrophages in areas containing necrotic cellular debris." (PMID 31022918, 2019). "The expression of CD68, a marker of macrophages 27, was measured in the primary tumor bed, surgical margin, and peritoneal metastatic lesions as well adjacent peritoneal tissue (5 cm from the margin of a lesion)." (PMID 31632482, 2019). "Increased infiltration of CD68+ TAMs in tumor tissues was correlated with recurrence in patients with RCC." (PMID 31192136, 2019). "Further staining for T cells (CD3) and macrophages (CD68) in additional serial sections found that these immune cells were also abundant in the tumor stroma concurrent with stromal miR-142-3p-positive cells." (PMID 31921386, 2019). "Likely, in the comparison between GA and neoplasia, PD-L1 Tii, B7-H3 Tum, B7-H3 Tii, B7-H4 Tii, and CD68 expression levels were notably different." (PMID 30813210, 2019). "Two of the most studied anti-inflammatory and pro-tumor cells are the Gr-1+/CD11b+ (MDSCs) and CD68+ (TAMs) cells." (PMID 31762937, 2019). "Pre-chemotherapy CD68 staining correlated positively with baseline SUVmax, and negatively with the percent of viable tumor cells in post-chemotherapy resection samples." (PMID 30999901, 2019). "We next stained consecutive slides of the tumor periphery from patients with the highest content of CD68+ TAMs (n = 10) for HLA-DR, a marker previously applied to identify M1-like TAMs in NSCLC14,15." (PMID 31383898, 2019). "IHC staining results also revealed that PD-L1 expression and tumor-infiltrating macrophage marker CD68 appeared in the tumor before BRAF and MEK inhibitors treatment in December 2013." (PMID 30633154, 2019). "The number of CD68+ cells was positively correlated with tumor size and Knosp grade, and the authors found CD68+ cells to be more numerous in sparsely granulated GH and null cell tumors compared to densely granulated GH and corticotroph tumors." (PMID 31640258, 2019).
tumor (continued). "In TKI-naive group, greater tumour infiltration of TIM-3+ CD3+ T cells and M2-polarised macrophages (CD204+ CD68+ cells) were significantly associated with poorer PFS with IM." (PMID 31607749, 2019). "They showed that CD68+ and B7–H4+ circulating macrophages correlated with tumor size and lymph node metastasis." (PMID 30781683, 2019). "In the CD68+ group, only 19/53 (35.8%) patients suffered overall tumour recurrence, whereas in the CD68− group, 4/5 (80.0%) patients had recurrent disease (p = 0.05)." (PMID 31170995, 2019). "We then examined the relationship between the expression of these negative costimulatory molecules and the densities of infiltrating CD8- and CD68-positive cells in the GA and neoplasia phases." (PMID 30813210, 2019). "All of these patient samples showed recruitment of TAMs (CD68 positive staining) to the tumor microenvironment." (PMID 31383898, 2019). "The percentage of CD68+ HLA-DR+ M1 macrophages in tumor mass was 50.2% while that in tumor matrix was 65.5%." (PMID 31379842, 2019). "All studies used immunohistochemistry to detect CD68- or CD163-positive macrophages in tumor specimens." (PMID 31528210, 2019). "In contrast, the appearance of Caspase 3 and CD68 proteins on tumor tissues of the IT group was significantly higher than the INT group (p<0.01)." (PMID 32695310, 2019). "Anti-CD68 highlighted a mild macrophage infiltrate within and around the tumor with increased density of staining within the foci of tumor necrosis, consistent with increased macrophage concentration in areas containing increased cellular debris." (PMID 31022918, 2019). "The relationship between the pan-macrophage marker CD68 and some other pro-tumor macrophage markers, such as CD163, CD204 and CD206, has been studied previously." (PMID 31528210, 2019). "The number of CD68+ macrophages was much higher in the mice tumor tissues inoculated with the MDA-MB-231 cells than mice transplanted with the MCF-7 cells." (PMID 31853223, 2019). "The CD68+ HLA-DR+ M1-like macrophages and CD68+ macrophages were counted in 40 tumor mass regions and 40 tumor matrix regions selected from these HCC specimens." (PMID 31379842, 2019). "Some authors have suggested possible benefit from immunotherapy basing on the expression in the microenvironments of PCs of lymphocytes infiltrating the tumor, death ligand 1 and CD68+ as potential biomarkers target in cancer therapies." (PMID 31142320, 2019). "CD3+ T cells and CD68+ tumor-infiltrating macrophages/dendritic cells were detected in about half of the samples (45.5 and 59.1%, respectively), whereas CD8+ cytotoxic T cells were rarely present in the tumors (18.2%)." (PMID 31134150, 2019). "Through multiplex IF and conventional IHC, our group was able to identify and enumerate CD68+ TAMs present in the tumor samples from HCC patients." (PMID 31552039, 2019). "ICC analysis revealed poor concordance when comparing CD68 counts between larger tumor and tumor core biopsies." (PMID 31772388, 2019). "D) The percentage of CD68+ CD14+ cells is increased following tumour polarisation, compared to the mean of unpolarised cells (RED)." (PMID 31462392, 2019). "The CD163+ and CD68+CD206+ macrophages were found to continuously upregulate PDL1 as they became more embedded in the tumor-nest." (PMID 31477692, 2019). "Similar results were obtained by FACS analysis of the dissociated fresh ATC tumor, with 13.5% of total cells being positive for CD68." (PMID 30938231, 2019). "The tumor cells show positive immunoreactivity against S100 protein, CD68, carcinoembryonic antigen (CEA), and vimentin." (PMID 30989009, 2019). "We found that SIRT4 expression in CD68+ TAMs from tumours with grades III–IV was much lower than that from tumours with grades I–II." (PMID 31744516, 2019). "A higher amount of CD68‐, CD163‐ and CD206‐positive GAMs in the vital tumor core was associated with beneficial patient survival." (PMID 30506802, 2019).
tumor (continued). "In our study, CD68-positive macrophages were found to represent a prominent component of the viable tumor regions of many of the STS cases." (PMID 30999901, 2019). "Considering B7-H3 can induce tumor necrosis factor-alpha (TNF-α) expression in monocyte-macrophage cells, we assume that B7-H3 is likely to promote the production of some cytokines to influence tumor progression through interaction with CD68-positive cells." (PMID 30813210, 2019). "The majority of the CD68+IRF8+ macrophages (78%) had tumor cells within 20 μm radius of their nucleus." (PMID 31477692, 2019). "By immunohistochemical analysis, in tumor tissue, the median level of CD68 + cells/ HPF was 27 (range, 7–83), and the median level of CD163 + cells/HPF was 17 (range, 2–78)." (PMID 31694577, 2019). "We observed that CD44 and ALDH1 were also expressed by macrophages, and we therefore conducted IHC studies using CD68 to specifically identify the proportion of tumor macrophages." (PMID 30999901, 2019). "First, digitized images of paraffin-embedded whole axial cross-sections of the tumor collected at CSF1R trial endpoints were analyzed by counting all TAMs according to their CD68 staining to measure general response to the CSF1R inhibitor." (PMID 30696910, 2019). "The tumor cells showed robust coarse immunopositivity for CD68 and displayed a variable Ki-67 proliferative index." (PMID 31906059, 2019). "We analyzed core biopsies from 87 pre-therapeutic BC patients for total TILs and the following subtypes: CD3+, CD4+, CD8+, CD20+ and CD68+ cells in correlation to clinicopathological parameters and disseminated tumor cells (DTCs) in the bone marrow." (PMID 30717704, 2019). "In other words, cases with more CD68+ cells at biopsy had fewer viable tumor cells at resection, suggesting a better response to chemotherapy." (PMID 30999901, 2019). "Here, we show that accumulation of PD-L1+ tumor and stromal cells is associated with local high infiltration of CD8+ T cells and CD68+/CD163+ TAMs." (PMID 30899426, 2019). "TAMS (as identified by CD68 antibodies) are thought to be driven by immunosuppressive cytokines such as IL-10 and TGF-beta and have been associated with suppressing T cell tumor response and promoting tumor growth and spread." (PMID 31903172, 2019). "Our data revealed a notable increase of LDs in CD68+CD206+ tumor‐infiltrating myeloid cells in CRC patients when compared with adjacent non‐tumor tissue (Control)." (PMID 31602788, 2019). "Correlation between CD68+ stained cells in the larger tumor specimen compared with small biopsies was met when two central or two peripheral biopsies were used." (PMID 31772388, 2019). "Patients with tumours marked by appearance of TILs and CD68+ TAMs showed an improved 1-, 3- and 5-year recurrence-free survival (all p ≤ 0.05)." (PMID 31170995, 2019). "The splenic CD68+ macrophages were isolated from tumour-bearing mice on day 15 following tumour inoculation (termed as tumour-bearing macrophage)." (PMID 31519961, 2019). "A significantly higher percentage of the CD68+CD206+ and the CD68+IRF8+ macrophages had tumor cells within a 10 μm radius (median effective percentages of 31 and 27%, respectively)." (PMID 31477692, 2019). "Immunofluorescence studies indicated that fewer pan macrophages (CD68+CD163+) are present in the lung of STAT6−/− tumor-bearing mice than their WT littermates." (PMID 31798581, 2019). "On the other hand, a decline was noted in the proportions of CD68+MHCII+F4/80+ M1 and CD68+MHCII+CD86+CD206+ M2 macrophages in the tumor-infiltrate and spleen of Dll1-ablated mice." (PMID 30940183, 2019). "High expression of CD163 at tumor invasive front was significantly associated with tumor grade, LVI, TI, LNM and TNM stage (P < 0.05, respectively), while high expression of CD68 at tumor invasive front was only significantly associated with LNM (P = 0.016)." (PMID 30927925, 2019).